ECT2L (epithelial cell transforming 2 like)
Description:
May act as a guanine nucleotide exchange factor (GEF).
Synonyms: C6orf91; LFDH; ARHGEF32; FBXO49; dJ509I19.2; dJ509I19.3; dJ509I19.5
Tractability: No criterion of Open Targets' tractability assessment is met for any kind of drug.
Gene: Protein-coding gene on chromosome 6 (138,795,911 to 138,904,070, forward strand). Ensembl gene ENSG00000203734.
Subcellular location (Human Protein Atlas): Nucleoplasm; Vesicles
Gene Ontology:
Molecular function: guanyl-nucleotide exchange factor activity
Genetic constraint (gnomAD): Loss-of-function variants: 106 observed, 110.55 expected, observed/expected ratio (o/e) 0.96, 90% interval 0.82 to 1.13. The upper end of that interval is the gene's LOEUF score, 1.13, which puts it in group 4 of 6, group 1 being the genes least tolerant of losing a copy. Missense variants: 947 observed, 1,034.7 expected, observed/expected ratio (o/e) 0.92, 90% interval 0.87 to 0.97. Synonymous variants: 355 observed, 374.82 expected, observed/expected ratio (o/e) 0.95, 90% interval 0.87 to 1.03.
Homologues: Orthologues: chimpanzee ECT2L (99% identical), macaque ECT2L (97% identical), pig ECT2L (84% identical), rabbit ECT2L (80% identical), mouse Ect2l (78% identical), rat Ect2l (76% identical), guinea pig ECT2L (75% identical), zebrafish ect2l (45% identical), Caenorhabditis elegans exc-5 (9% identical), Caenorhabditis elegans frm-3 (6% identical). Paralogues in human: FGD6 (14% identical), FGD5 (14% identical), FARP2 (12% identical), FGD4 (12% identical), FARP1 (11% identical), FGD1 (11% identical), FGD2 (10% identical), FGD3 (10% identical), ARHGEF39 (7% identical), FRMD7 (6% identical).
Diseases named in the same sentence as ECT2L in open-access papers:
ECT2L is named in the same sentence as 6 diseases in open-access papers, as found by Europe PMC text mining. Sharing a sentence is not in itself a finding about the gene and the disease. The quoted sentences say what the papers report.
acute lymphoblastic leukemia (1 paper, 2025). Leukemia with an acute onset, characterized by the presence of lymphoblasts in the bone marrow and the peripheral blood. "Additionally, recurrent somatic mutations in ECT2L have been identified in early T-cell precursor acute lymphoblastic leukemia." (PMID 40431499, 2025).
gastric cancer (1 paper, 2018). A primary or metastatic malignant neoplasm involving the stomach. "As expected, higher expression of ECT2-L was related to poor overall survival in patients with lung, breast, ovarian, and gastric cancer." (PMID 29706628, 2018).
liver cancer (1 paper, 2018). An epithelial or non-epithelial malignant neoplasm that arises from the liver. "Additionally, we also analyzed the expression level of ECT2-L in various large scale studies from TCGA, and found ECT2-L is evidently elevated in multiple cancers, including lung, breast, colon, renal, esophageal, liver cancer, and so on." (PMID 29706628, 2018).
cancer (7 papers, 2018 to 2025). A tumor composed of atypical neoplastic, often pleomorphic cells that invade other tissues. "ECT2L mutations have been infrequently reported in cancer and, to our knowledge, this is the first study reporting high mutational frequency in diffuse‐type GC, suggesting a potential role in its progression." (PMID 40926327, 2025). "The ECT2L gene (epithelial cell transforming 2 like) regulates Rho protein signal transduction and has been linked to both cancer progression and cholesterol metabolism." (PMID 40431499, 2025). "Intriguingly, we applied Kaplan–Meier Plotter to analyze the overall survival of cancer patients with distinct ECT2-L levels using datasets from large scale screening." (PMID 29706628, 2018). "In addition to the likely pathogenic variant on the DCC gene, we also identified a truncating VUS in the ECT2L gene, along with 11 variants classified as VUS in cancer-related genes." (PMID 36077770, 2022). "They correspond to 63 unique genes, as some genes are prioritized in different cancers (e.g., ECT2L and HLA-DQA2 are prioritized in all four cancers), highlighting that different cancers share some rewired genes." (PMID 30778056, 2019).
ECT2L also shares sentences with these, for which no sentence is quoted: breast carcinoma (1 paper); gallbladder carcinoma (1).